CLCN5 (Cl-/H+ antiporter 5)
Diseases named in the same sentence as CLCN5 in open-access papers (continued):
Sharing a sentence is not in itself a finding about the gene and the disease.
renal carcinoma (2 papers, 2023 to 2025). A carcinoma arising from the epithelium of the renal parenchyma or the renal pelvis. "Considering the diminished expression of CLCN5 in renal cancer tissues and cell lines (A498 and 786-O), we initially elevated its expression in these cells through plasmid transfection." (PMID 40765554, 2025). "Next, we constructed stable knockdown CLCN5 renal cancer cell lines and showed the same results with siRNA in fluorescence microscopy analysis flow cytometry." (PMID 40765554, 2025). "Our studies found that CLCN5 played a role in influencing the progression of renal cancer through the promotion of fatty acid degradation in renal cancer cells." (PMID 40765554, 2025). "Additionally, the potential link between chloride ion and lipid metabolism in renal cancer need to be further explored as CLCN5 is a chloride ion channel." (PMID 40765554, 2025). "Bioinformatics and cell experiments had demonstrated that EHHADH might be a unique downstream and mediated lipid degradation of CLCN5 in renal cancer cells." (PMID 40765554, 2025). "CLCN5 can significantly reduce lipid storage, and EHHADH may be a downstream of CLCN5 in renal cancer cells." (PMID 40765554, 2025). "In this study, we found that CLCN5 overexpression could significantly reduce lipid storage in renal cancer cells." (PMID 40765554, 2025).
renal Fanconi syndrome (2 papers, 2015 to 2019). "In order to rule out monogenic forms of renal Fanconi syndrome, molecular genetic screening for variants in CLCN5, OCRL1 and CTNS was initially performed in Patient 1 (P1)." (PMID 31435670, 2019).
renal fibrosis (2 papers, 2022 to 2024). A final common manifestation of a wide variety of chronic kidney diseases characterized by glomerulosclerosis and tubulointerstitial fibrosis. "Our data revealed that Col I/IV mRNA levels, both increased in renal fibrosis, were higher in CLCN5 KD cells than in control or rWT cells (4.9- and 4.0-fold increase, respectively, P < 0.01)." (PMID 38670633, 2024). "Our data showed that Clcn5 KO (Clcn5−/−) and heterozygous (Clcn5+/−) mice already present evidence of renal fibrosis at 3 mo of age, reproducing this DD1 feature." (PMID 38670633, 2024). "Specific staining of collagen type IV (Col IV), which is increased in renal fibrosis, revealed higher extracellular deposition of Col IV in mice lacking Clcn5 (Clcn5+/− and Clcn5−/−) compared with Clcn5+/+ mice (1.14 μm versus 0.81 μm, P < 0.01), reproducing the results from our CLCN5 KD cells." (PMID 38670633, 2024). "Finally, global assessment considering Sirius Red/Fast Green and Col IV staining, amongst others, confirmed that 3-mo-old Clcn5+/− and Clcn5−/− mice already present higher levels of renal fibrosis than Clcn5+/+ mice (no fibrosis: 100% versus 33.3%, fibrosis degree >1: 66.6% versus 0%, P < 0.01)." (PMID 38670633, 2024).
rickets (2 papers, 2015 to 2024). Bone softening and weakening usually caused by deficiency or impaired metabolism of vitamin D. Deficiency of calcium, magnesium, or phosphorus may also cause rickets. "It is noteworthy, however, that in children with CLCN5 mutations the clinical finding of rickets were present in 9 out of 21, almost two time more frequent than in children without CLCN5 mutations where only 2 out of 9 presented with rickets." (PMID 26389017, 2015).
X-linked disease (2 papers, 2018 to 2023). X-linked form of disease. "Similar renal tubular defects are also characteristics of Dent-1, another X-linked disease that is caused by mutations in the gene CLCN5 that encodes for the endosomal proton-chloride exchanger ClC-5." (PMID 29300302, 2018).
clear cell renal cell carcinoma (1 paper, 2025). "Therefore, the present research has unveiled a crucial regulatory mechanism for lipid metabolism of CLCN5/EHHADH signal in clear cell renal cell carcinoma." (PMID 40765554, 2025).
colitis (1 paper, 2017). Inflammation of the colon. "Vice versa, increased susceptibility to dextran sulfate sodium-induced colitis was found in Clcn5 knockout mice." (PMID 28348980, 2017).
developmental delay (1 paper, 2020). "A study showed CLC proteins (including CLC‐5 encoded by the CLCN5 gene) could regulate electrical excitability of neurons, thus, the relationship between developmental delay and CLCN5 mutations may exist." (PMID 32495484, 2020).
kidney cancer (1 paper, 2025). Primary or metastatic malignant neoplasm involving the kidney. "The expression profiles of CLCN5 in multiple GEO datasets of kidney cancer (GSE44035, GSE66272, and GSE53757) were further investigated." (PMID 40765554, 2025). "Subsequently, we conducted verification studies to assess the role of CLCN5 on kidney cancer cells." (PMID 40765554, 2025). "Based on these results, we prioritized our focus on CLCN5 in the pathogenesis and progression due to the lack of previous reports in kidney cancer." (PMID 40765554, 2025).
lung carcinoma (1 paper, 2021). "While CLCN5 was unique to lung cancer participants compared to stable COPD participants, targeted by four under-expressed miRNAs." (PMID 34071592, 2021).
metastatic prostate carcinoma (1 paper, 2015). A carcinoma that arises from the prostate gland and has spread to other anatomic sites. "Four genes in particular, MALAT1, CLCN5, MLL3, and SLC25A36, that were up-regulated in metastatic prostate cancer compared to primary prostate cancer were also displayed an enhanced expression in PC3-WT osteoblast co-cultures and PC3-SostKO osteoblast co-cultures compared to PC3 alone." (PMID 27600237, 2015).
nephrotic syndrome (1 paper, 2015). A collection of symptoms that include severe edema, proteinuria, and hypoalbuminemia; it is indicative of renal dysfunction. "The CLCN5 gene, and if negative, the OCRL1 gene should be analyzed before considering a renal biopsy in males with nephrotic range proteinuria and no clinical signs of nephrotic syndrome." (PMID 26108450, 2015).
obsessive-compulsive disorder (1 paper, 2019). A disorder characterized by the presence of persistent and recurrent irrational thoughts (obsessions), resulting in marked anxiety and repetitive excessive behaviors (compulsions) as a way to try to decrease that anxiety. "The gene CLCN5 encodes the protein chloride channel 5 (Clc-5), and one study found the gene CLCN5 to be differentially methylated in brain tissue from obsessive-compulsive disorder subjects and controls." (PMID 31818333, 2019).
ovarian carcinoma (1 paper, 2020). A malignant neoplasm originating from the surface ovarian epithelium. "MIR502 is located in the third intron of the CLCN5 gene, and it shows a strong positive correlation with CLCN5 in ovarian cancer." (PMID 32660514, 2020).
Pendred syndrome (1 paper, 2011). Pendred syndrome (PDS) is a clinically variable genetic disorder characterized by bilateral sensorineural hearing loss and euthyroid goiter. "The thyroidal phenotype in ClCn5-deficient mice is similar to that in Pendred syndrome, suggesting that ClCn5 could participate in mediating apical iodine efflux or iodine/chloride exchange." (PMID 21689387, 2011).
renal cell carcinoma (1 paper, 2025). "To elucidate the potential role and biological effects of CLCN5 in renal cell carcinoma, we conducted in vitro functional experiments." (PMID 40765554, 2025).
vasculitis (1 paper, 2024). "In addition, two of the three patients who underwent genetic sequencing were found to have abnormal genetic deoxyribonucleic acid (DNA) sequences, including VWF mutation in patient 3 and CLCN5 mutation in patient 10, which could not explain the occurrence of vasculitis." (PMID 38357518, 2024).
kidney disease (9 papers, 2011 to 2025). "Since our patient had advanced kidney disease at a young age with a novel CLCN5 variant, our case serves as an example that similarly affected families should receive anticipatory guidance about expectations of Dent disease." (PMID 39610999, 2024). "Our case report is of significance as we describe a young male with a novel pathogenic variant in CLCN5 and more advanced kidney disease than observed in medical literature for individuals with Dent 1 in childhood." (PMID 39610999, 2024). "In fact, pathogenic variants in various genes responsible for inherited kidney diseases (patients with NPHS1, EYA1, LAMB2, and CLCN5 gene mutations) were detected by NGS in our study." (PMID 31364286, 2019).
cancer (6 papers, 2015 to 2025). A tumor composed of atypical neoplastic, often pleomorphic cells that invade other tissues. "miR-362-3p is an intronic miRNA located in intron 3 of the CLCN5 gene on chromosome X. The biological role of miR-362-3p has been investigated in several human cancers." (PMID 32432112, 2020). "Additionally, the results from the IHC analysis of tumor and tumor-adjacent tissue pairs showed the downregulation of CLCN5 in cancer tissues." (PMID 40765554, 2025).
tumor (6 papers, 2020 to 2025). "Moreover, the ROC curve analysis demonstrated that CLCN5 exhibits significant diagnostic potential in tumor tissues, as well as subgroups of tumor stages and grade subgroups." (PMID 40765554, 2025). "Furthermore, diminished expression of CLCN5 was associated with a reduced overall survival (OS) and higher tumor clinicopathological grade." (PMID 40765554, 2025). "In vitro experiments demonstrated that CLCN5 overexpression significantly impacts fatty acid oxidation and inhibits tumor proliferation, metastasis, migration, and invasion in ccRCC." (PMID 40765554, 2025). "In our study, CLCN5 expression was significantly reduced, and CLCN5 expression was negatively correlated with pathological grades and tumor stages in ccRCC." (PMID 40765554, 2025). "Tumor tissue transcriptome analysis revealed reduced CLCN5 expression in both the TCGA-KIRC and GEO datasets." (PMID 40765554, 2025). "The qRT-PCR and WB analyses revealed that the expression of CLCN5 was significantly decreased in tumor samples compared to controls." (PMID 40765554, 2025). "We predicted NRF1 as a transcription factor regulating CLCN5, and ChIP-seq data of various tumour cells verified the binding peak between NRF1 and CLCN5." (PMID 32660514, 2020). "MiR‐502‐5p is located at chromosome Xp11.23 and belongs to the CLCN5 region and numerous miRNAs of which have been confirmed to involve in divergent types of tumours." (PMID 31971654, 2020). "In vitro experiments demonstrate that modulating CLCN5 expression could significantly impacts fatty acid oxidation, tumor proliferation, metastasis, migration, and invasion in ccRCC." (PMID 40765554, 2025). "Collectively, these findings indicate that downregulation of CLCN5 promotes lipid accumulation in ccRCC, whereas reinstating CLCN5 expression may impede tumor progression through enhanced lipid degradation." (PMID 40765554, 2025). "Moreover, we have furnished preliminary evidence indicating that CLCN5 could inhibit the tumor proliferation, metastasis, migration, invasion, and promote lipid elimination in ccRCC." (PMID 40765554, 2025).
genetic disease (3 papers, 2018 to 2025). "These approaches allowed to establish genetic diagnoses in 24% of the patients screened, widened the spectrum of genetic disease entities presenting with SRNS phenotype (COL4A3-5, CLCN5), and contributed to the discovery of new disease causing genes (MYOE1, PTPRO)." (PMID 30065916, 2018).
CLCN5 also shares sentences with these, for which no sentence is quoted: Dent disease type 1 (27 papers); renal failure (5); X-linked recessive hypophosphatemic rickets (5); Bartter syndrome (4); Dent disease type 2 (4); Fanconi syndrome (4); focal segmental glomerulosclerosis (4); hypophosphatemia (4); multiple myeloma (3); osteopetrosis (3); autism (2); cyst (2); cystinuria (2); epilepsy (2); Fabry disease (2); Intellectual disability (2); microcephaly (2); Myotonia congenita (2); nephropathies (2); neurological disease (2); renal tubular acidosis (2); Alport syndrome (1); Aminoaciduria (1); autosomal dominant hypophosphatemic rickets (1); autosomal dominant tubulointerstitial kidney disease (1); autosomal recessive hypophosphatemic rickets (1); bone disorder (1); chronic renal failure (1); ciliopathies (1); colon cancer (1).
A further 48 diseases each share a sentence with CLCN5 in 1 paper.